CCN3 (cellular communication network factor 3)
Diseases named in the same sentence as CCN3 in open-access papers (continued):
Sharing a sentence is not in itself a finding about the gene and the disease.
glioma (6 papers, 2004 to 2024). A benign or malignant brain and spinal cord tumor that arises from glial cells (astrocytes, oligodendrocytes, ependymal cells). "The antibodies were applied in indirect immunofluorescence tests and immunoenzyme assays on glial tumor cell line, G59, and its CCN3-transfected variant G59/540 and the adrenocortical cell line, NCI-H295R." (PMID 15361251, 2004). "Meanwhile, Notch1 pathway‐related genes, including Maml2, Ccn3, Fat4, Cdh6, and Ptp4a3, exhibited similar expression trends and may be intimately linked to glioma development." (PMID 39544152, 2024). "EGFR, BCAN, SOX2, PTN and CCN3 were found to be highly elevated in the glioma tumorous tissue with prominent fold change value, while other DE-ARGs, such as CLU, SCG3, showed no distinct expression alteration." (PMID 39033204, 2024). "CCN3 has anti-tumor effects in breast cancer, colorectal tumors, kidney cancer, glioma, and leukemia." (PMID 33833779, 2021). "Therefore, the antiproliferative activity of CCN3 was not restricted to glioma cells but could be considered as a genuine common feature." (PMID 16504021, 2006).
osteoarthritis (6 papers, 2015 to 2022). A noninflammatory degenerative joint disease occurring chiefly in older persons, characterized by degeneration of the articular cartilage, hypertrophy of bone at the margins and changes in the synovial membrane. "The matricellular protein NOV/CCN3, is implicated in osteoarthritis (OA) and targeted mutation of NOV in mice (Novdel3) leads to joint abnormalities." (PMID 25541297, 2015). "Recently, CCN3 has emerged as a critical regulator in a variety of diseases, including immune-related diseases, including rheumatology arthritis, osteoarthritis, and systemic sclerosis." (PMID 34393649, 2021). "In contrast, it has been shown that CCN3 exhibits a protective role in osteoarthritis and disruption of CCN3 in aged male mice results in osteoarthritis-like disease." (PMID 32455138, 2020). "In the present study, we also found the CCN3 expression in the synovial samples from RA and osteoarthritis patients and CCN3 was much higher in the synovial tissue from RA compared to that in OA." (PMID 32455138, 2020). "HMGB1 was negatively correlated with CCN3 in osteoarthritis, and HMGB1 is involved in the protective effect of CCN3 in OA." (PMID 31454155, 2019). "Our data showed that HMGB1 was negatively correlated with CCN3 expression in IL‐1β‐induced osteoarthritis responses." (PMID 31454155, 2019). "Previous studies showed that CCN3 was upregulated in RA synovial samples and osteoarthritis." (PMID 32455138, 2020). "CCN3 knockout mice displayed osteoarthritic changes in knee articular cartilage, suggesting that CCN3 may suppress osteoarthritis progression by maintaining the differentiated phenotype of articular cartilage." (PMID 32455138, 2020). "This study explored the new protective mechanism of CCN3 in osteoarthritis and noted that CCN3 could serve as a novel potential therapeutic target for osteoarthritis." (PMID 31454155, 2019). "Therefore, CCN3 may play distinct roles in RA and osteoarthritis, two common types of chronic arthritis." (PMID 32455138, 2020). "Substantial evidence implicates four of the proteins (CCN1, CCN2, CCN3 and CCN4) in the inflammatory pathologies of rheumatoid arthritis (RA) and osteoarthritis (OA)." (PMID 33919365, 2021). "High‐mobility group box 1 was negatively correlated with CCN3 in IL‐1β‐induced osteoarthritis responses, and HMGB1 is involved in the protective effect of CCN3 in OA." (PMID 31454155, 2019). "Recent studies have reported that osteoarthritis expresses a specific gene when exposed to excessive mechanical stress; however, high expression of CCN3 was observed for OA irrespective of age and weight." (PMID 36499638, 2022). "In conclusion, in this study, it was found that the high expression of CCN3 is not related to load or aging but is correlated with osteoarthritis." (PMID 36499638, 2022). "In addition, CCN3 is identified as a protective factor in cartilage by inhibiting the PI3K/AKT/mTOR pathway, alleviating the deterioration of osteoarthritis." (PMID 32455138, 2020). "Our study presents new mechanisms of CCN3 in osteoarthritis and indicates that CCN3 can serve as a novel potential therapeutic target for osteoarthritis." (PMID 31454155, 2019).
renal fibrosis (6 papers, 2016 to 2023). A final common manifestation of a wide variety of chronic kidney diseases characterized by glomerulosclerosis and tubulointerstitial fibrosis. "While studies have linked Ccn3 to integrin and Notch1 mediated signaling and prevention of renal fibrosis, the role of Ccn3 in the heart post injury is virtually unexplored." (PMID 36998974, 2023). "Comparable to CCN3/NOV in renal fibrosis, and opposite to fibrotic CCN2/CTGF, CCN5/WISP-2 is anti-fibrotic in the heart." (PMID 34063397, 2021). "CCN3/NOV is known to have an anti-fibrotic action in renal fibrosis models, downregulating CCN2/CTGF and decreasing the expression and accumulation of ECM proteins." (PMID 34063397, 2021). "In renal fibrosis, CCN3 suppresses TGF-β1-induced extracellular matrix accumulation." (PMID 32455138, 2020). "Furthermore, we report that the extent of renal fibrosis, in terms of Col I, TGFβ, CCN2 and CCN3 expression and collagen I immunostaining, increases with increasing body temperature during ischemia and ischemia-time." (PMID 27007127, 2016).
atherosclerosis (5 papers, 2014 to 2023). A disease characterized by the build-up of fatty material and calcium deposition in the arterial wall resulting in partial or complete occlusion of the arterial lumen. "Our previous studies have implicated a protective role of myeloid CCN3 against atherosclerosis and non-alcoholic fatty liver disease (NAFLD)." (PMID 36670446, 2023). "Studies have shown that CCN3 loss leads to a significant increase in lipid uptake and foam cell formation in macrophages, while overexpression can inhibit atherosclerosis." (PMID 35250960, 2022). "For example, deficiency of NOV (also known as CCN3), a down-regulated cDEG when comparing M-LPSlate and M-IFNγ with M0, increases foam cell formation and exacerbates atherosclerosis in mice." (PMID 31921150, 2019). "Our recent in vivo studies identified matricellular protein CCN3 as a negative regulator of experimental atherosclerosis." (PMID 36670446, 2023). "The overexpression of CCN3 by adenovirus-mediated gene expression in vivo showed beneficial effects in relieving atherosclerosis." (PMID 24722330, 2014). "Using a mouse model of atherosclerosis, the mRNA and protein levels of CCN3 decreased by 72.2% (p = 0.041) and 86.4% (p = 0.036), respectively, compared with levels in wild-type control mice, respectively." (PMID 24722330, 2014). "Our data also implied that manipulation of CCN3, such as adenovirus-mediated overexpression of CCN3 in vivo, attenuated the inflammatory progress in atherosclerosis." (PMID 24722330, 2014). "Taken as a whole, we identified that CCN3 contributed to the control and coordination of inflammatory processes in atherosclerosis." (PMID 24722330, 2014). "CCN3 expression levels in the left common carotid artery in a mouse model of atherosclerosis were analyzed." (PMID 24722330, 2014). "In the present study, we provide evidence that CCN3 is a novel regulator of the inflammatory process of atherosclerosis." (PMID 24722330, 2014). "In the present study, we found that loss of CCN3 was correlated with VCAM-1 and ICAM-1 expression in atherosclerosis, and the overexpression of CCN3 significantly inhibited the expression of these genes." (PMID 24722330, 2014). "Building on our reported in vivo evidence demonstrating the inhibitory function of myeloid CCN3 in atherosclerosis, we tested our hypothesis that myeloid CCN3 mitigates aortic valve calcification, thus a protective factor against CAVD." (PMID 36670446, 2023). "In atherosclerosis, CCN3 inhibits macrophage foam cell formation." (PMID 32455138, 2020). "Overall, CCN3 has shown anti-inflammatory effects in atherosclerosis." (PMID 24722330, 2014). "Additionally, we found that overexpression CCN3 significantly increased the body weights in mouse models of atherosclerosis." (PMID 24722330, 2014). "However, further investigations are warranted to delineate the molecular mechanism of CCN3 in regulating the inflammatory progress in atherosclerosis." (PMID 24722330, 2014). "Interestingly, CCN3 was revealed to interact with IL-33, which has been suggested to have protective effects against atherosclerosis." (PMID 24722330, 2014). "In the present study, we aimed to investigate the role of CCN3 in atherosclerosis." (PMID 24722330, 2014). "Overexpression of CCN3 may relieve the inflammation response in and inhibit the progress of atherosclerosis." (PMID 24722330, 2014). "We hypothesized that the overexpression of CCN3 might have beneficial effects in improving atherosclerosis." (PMID 24722330, 2014). "This suggests that CCN3 is a promising target for atherosclerosis treatment." (PMID 24722330, 2014). "CCN3 overexpression is associated with control of inflammatory processes and reversion of dyslipidemia in the process of atherosclerosis, which implies that CCN3 may be a promising target in the treatment of atherosclerosis." (PMID 24722330, 2014).
atherosclerosis (continued). "Lately, CCN3 has been reported to be a novel modulator of endothelial inflammation, suggesting that CCN3 might have a potential role in regulating atherosclerosis progress." (PMID 24722330, 2014). "We aimed to explore the potential roles of CCN3 in inflammation in atherosclerosis." (PMID 24722330, 2014). "We further showed that CCN3 expression was inhibited in atherosclerosis." (PMID 24722330, 2014). "To test whether overexpression of CCN3 alleviates atherosclerosis, we constructed recombinant adenovirus expressing CCN3, for in vivo injection." (PMID 24722330, 2014). "To investigate whether CCN3 is capable of regulating the inflammatory factors in atherosclerosis, we first analyzed the expression of MMP-2 and MMP-9 by ELISA." (PMID 24722330, 2014). "However, the role of CCN3 in atherosclerosis, which is characterized by vascular inflammation, remains unclear." (PMID 24722330, 2014). "Whether CCN3 expression is altered in atherosclerosis is poorly understood." (PMID 24722330, 2014). "However, the precise role of CCN3 in atherosclerosis is under-explored." (PMID 24722330, 2014). "We aimed to explore the effect of the overexpression of CCN3 on CCN1 and CCN2 levels in atherosclerosis." (PMID 24722330, 2014). "As expected, the overexpression of CCN3 alleviated the dysregulated lipid metabolism by reducing levels of cholesterol, triglycerides, and LDL-C, and by increasing the level of HDL-C in an atherosclerosis mouse model." (PMID 24722330, 2014). "In the present study, we observed that the overexpression of CCN3 downregulated gene expression of CCN1 and CCN2, indicating that the three CCN proteins had positive or negative effects in atherosclerosis." (PMID 24722330, 2014).
chondrosarcoma (5 papers, 2005 to 2023). A malignant cartilaginous matrix-producing mesenchymal neoplasm arising from the bone and soft tissue. "In contrast, CCN3 expression has been associated with a more differentiated phenotype and better prognosis in chondrosarcoma." (PMID 22427255, 2012). "Nevertheless, as observed in osteo- and chondrosarcoma, CCN3 promotes TC-71 cell migration and invasion, decreasing adhesion on collagen type I and IV via integrin α2β1." (PMID 34228239, 2021). "Studies on a chondrosarcoma-derived cell line showed that CCN3 increases their migration and up-regulates MMP-13 expression and activity." (PMID 22427255, 2012). "CCN3 expression in chondrosarcoma was reported to be higher in well-differentiated tumors and associated with a better patient prognosis." (PMID 22427255, 2012). "Immunohistochemical analyses revealed that infiltrates of giant-cells within chondrosarcomas exhibited strong staining of CCN3." (PMID 22427255, 2012). "CCN1, CCN2, CCN3 and CCN4 are expressed in enchondromas and low-grade chondrosarcomas, whereas their expression diminishes as disease progresses to higher grades and less differentiated lesions." (PMID 34228239, 2021).
diabetes (5 papers, 2013 to 2022). "As an anti-fibrotic molecule in the CCN family, the gene expression of CCN3 showed a trend to being lower in the diabetes alone, HFD alone, and the HFD with diabetes group, each compared with the Chow group." (PMID 35038159, 2022). "Our results identify CCN3, a novel transcriptional target of FoxO1 in pancreatic β-cells, as a potential target for therapeutic intervention in the treatment of diabetes." (PMID 23705021, 2013). "A previous genomic study comparing the expression profile of islets from healthy donors to patients with type 2 diabetes reported a ∼2-fold increase in Ccn3 mRNA levels in diabetes (and G.C. Weir, personal communication)." (PMID 23705021, 2013). "Certainly, our results warrant closer examination of the role of CCN3 in diabetes." (PMID 23705021, 2013). "Moreover, CCN3 protein has antifibrotic effects in a diabetes model." (PMID 31170244, 2019). "Blocking CCN2 by CCN2Ab showed a trend only to normalisation of the CCN3 gene expression in diabetes alone and HFD alone groups, whereas CCN3 was clearly statistically significantly induced in the HFD + DM group." (PMID 35038159, 2022). "In that regard, another member of the CCN family, CCN3, is reciprocally regulated by CCN2 in a model of diabetes, in glomerular cell proliferation, and chondrocyte differentiation." (PMID 31170244, 2019).
glioblastoma (5 papers, 2004 to 2023). The most malignant astrocytic tumor (WHO grade IV). "In glioblastoma cells, CCN3 increased cell proliferation via a platelet-derived growth factor receptor A (PDGFRα)-dependent mechanism." (PMID 36737605, 2023). "Consistently, CCN3 could act as an antiproliferative protein by influencing the cell cycle of glioblastoma cells." (PMID 34393649, 2021). "Therefore, it remains to be determined what the exact contribution of EFEMP1 to Notch signaling is in TMZ-resistant glioblastoma cells in relation to other factors that can induce Notch signaling, including MAGP-1/2, CCN3, YB-1, DLL, and Jagged." (PMID 24495907, 2014).
hepatocellular carcinoma (5 papers, 2017 to 2023). A malignant tumor that arises from hepatocytes. "HSCs remodeling are positively related to CCN3 paracrine in hepatocellular carcinoma, which orchestrated the stroma-derived resistance to chemotherapy in HCC." (PMID 31805888, 2019). "On the other hand, CCN3 promotes tumor growth in hepatocellular carcinoma." (PMID 36737605, 2023). "However, when the expression levels of CCN2 and CCN3 in the same cases of hepatocellular carcinoma were compared, induction and reduction of the expression of CCN3 and CCN2, respectively, were observed, indicating the retention of the yin–yang regulatory system in these particular cases." (PMID 35682564, 2022).
liver fibrosis (4 papers, 2019 to 2023). "CCN1, CCN2, and CCN3 have each been studied to some degree in liver fibrosis." (PMID 35038159, 2022). "In hepatic fibrosis, CCN3 is increased expressed and mainly found in non-parenchymal cells, stimulate the migration of HSC and induce hepatocyte apoptosis, while the suppression of CCN3 enhanced expression of profibrotic marker proteins in primary HSC." (PMID 37166689, 2023). "CCN3 expression in non-cancerous hepatic tissues also correlated with the degree of liver fibrosis." (PMID 31029128, 2019).
rheumatoid arthritis (4 papers, 2020 to 2021). A chronic, systemic autoimmune disorder characterized by inflammation in the synovial membranes and articular surfaces. "This is in contrast to rheumatoid arthritis, where higher serum CCN3 was associated with higher disease activity and inflammatory markers." (PMID 33222687, 2020). "However, the role of CCN3 in rheumatoid arthritis (RA), a classic autoimmune and inflammatory disease, remains elusive." (PMID 32455138, 2020). "However, the role of CCN3 in rheumatoid arthritis (RA) remains elusive." (PMID 34393649, 2021).
systemic sclerosis (4 papers, 2020 to 2025). A chronic disorder, possibly autoimmune, marked by excessive production of collagen which results in hardening and thickening of body tissues. "In addition, the impact of CCN3 was also observed in systemic scleroderma, an autoimmune rheumatic disease characterized by excessive production and accumulation of collagen in the skin, small arteries, and internal organs." (PMID 32455138, 2020).
type 2 diabetes (4 papers, 2013 to 2022). "Furthermore, recent studies also showed that CCN3 was a novel adipokine, and it had emerged as a potential metabolic regulator in type 2 diabetes." (PMID 32455138, 2020). "Thus, in addition to CCN2, CCN1 and CCN3 may be novel therapeutic targets for NASH combined with type 2 diabetes with fibrosis." (PMID 35038159, 2022).
bipolar disorder (3 papers, 2016 to 2019). A disorder of the brain that causes unusual shifts in mood, energy, activity levels and the ability to carry out day-to-day tasks. "CCN3 is thought to regulate intracellular calcium levels, and aberrant calcium signaling has been implicated in both bipolar disorder and PP risk." (PMID 31849729, 2019).
hyperlipidemia (3 papers, 2017 to 2023). "Myeloid-specific knockout of CCN3 (Mye-CCN3-KO) and control mice were subjected to a single tail intravenous injection of AAV encoding mutant mPCSK9 (rAAV8/D377Y-mPCSK9) to induce hyperlipidemia." (PMID 36670446, 2023).
multiple sclerosis (3 papers, 2020 to 2023). A progressive autoimmune disorder affecting the central nervous system resulting in demyelination. "We investigated the profile of CCN3, a known regulator of immune function and a potential mediator of myelin regeneration, in multiple sclerosis in the context of disease state and disease-modifying treatment." (PMID 33222687, 2020). "In consistency with this, CCN3 is recently identified as a Treg-derived mediator and plays a role in remyelination in multiple sclerosis." (PMID 32455138, 2020). "CCN3 levels were increased in SSc, multiple sclerosis patients." (PMID 37749230, 2023).
preeclampsia (3 papers, 2014 to 2024). Preeclampsia is a hypertensive disorder of pregnancy that is characterized by new-onset hypertension with proteinuria presenting after 20 weeks of gestation, and depending on mild or severe forms may initially present with severe headache, visual disturbances, and hyperreflexia. "In contrast, evidence indicates the senescence-promoting role of CCN3 in trophoblast cells and chondrocytes, thus contributing to the pathogenesis of placental disease preeclampsia and the degeneration of articular cartilage, respectively." (PMID 38926528, 2024). "In conclusion, we found that CCN3 was conversely expressed in early preeclampsia and late AIP placentas." (PMID 33304321, 2020).